SOX21 (SRY-box transcription factor 21)
Description:
May play a role as an activator of transcription of OPRM1. Overexpression of SOX21 can up-regulate the OPRM1 distal promoter activity in mor-expressing neuronal cells. May play a role in ameloblast differentiation.
Synonyms: SOX25; SOX-A
Tractability: No criterion of Open Targets' tractability assessment is met for any kind of drug.
Gene: Protein-coding gene on chromosome 13 (94,709,622 to 94,712,545, reverse strand). Ensembl gene ENSG00000125285.
Subcellular location: Nucleus
Subcellular location (Human Protein Atlas): Nucleoplasm
Gene Ontology:
Molecular function: DNA binding; DNA-binding transcription activator activity, RNA polymerase II-specific; DNA-binding transcription factor activity; DNA-binding transcription factor activity, RNA polymerase II-specific; RNA polymerase II cis-regulatory region sequence-specific DNA binding
Biological process: stem cell differentiation; brain development; negative regulation of transcription by RNA polymerase II; neuron differentiation; positive regulation of transcription by RNA polymerase II; regulation of DNA-templated transcription; regulation of transcription by RNA polymerase II; developmental process
Cellular component: chromatin; nucleus
Genetic constraint (gnomAD): Loss-of-function variants: 4 observed, 4.82 expected, observed/expected ratio (o/e) 0.83, 90% interval 0.4 to 1.72. That is too few expected variants to judge how well the gene tolerates losing a copy. Missense variants: 356 observed, 307.99 expected, observed/expected ratio (o/e) 1.16, 90% interval 1.06 to 1.26. Synonymous variants: 221 observed, 157.35 expected, observed/expected ratio (o/e) 1.4, 90% interval 1.26 to 1.57.
Homologues: Orthologues: dog SOX21 (100% identical), macaque SOX21 (100% identical), pig SOX21 (100% identical), mouse Sox21 (99% identical), rat Sox21 (99% identical), tropical clawed frog sox21 (84% identical), zebrafish sox21b (72% identical), Drosophila melanogaster Sox21b (40% identical), Caenorhabditis elegans sox-4 (20% identical). Paralogues in human: SOX14 (58% identical), SOX1 (45% identical), SOX2 (41% identical), SOX3 (40% identical), SOX15 (30% identical), SOX8 (30% identical), SOX9 (28% identical), SOX10 (27% identical), SOX4 (27% identical), SOX17 (26% identical), SOX7 (26% identical), SOX11 (25% identical), and 8 more.
Diseases named in the same sentence as SOX21 in open-access papers:
SOX21 is named in the same sentence as 28 diseases in open-access papers, as found by Europe PMC text mining. Sharing a sentence is not in itself a finding about the gene and the disease. The quoted sentences say what the papers report.
glioma (11 papers, 2012 to 2024). A benign or malignant brain and spinal cord tumor that arises from glial cells (astrocytes, oligodendrocytes, ependymal cells). "A decreased SOX2/SOX21 ratio results in the loss of stem cell features in glioma cells." (PMID 38132438, 2023). "An increase of SOX21 in glioma cells reduced tumor size and inhibited glioma progression in vivo by forming complexes with SOX2 protein, therefore changing the balance between these proteins in the tumor." (PMID 37047365, 2023). "Forced expression of SOX21 induces cellular apoptosis in glioma cells and enables differentiation, preventing glioma formation." (PMID 38132479, 2023). "The increased expression of SOX21 in glioma cells inhibits the tumor progression and reduces the tumor size." (PMID 38132438, 2023). "It has been demonstrated that SOX6 expression is positively correlated with SOX21 expression in glioma patients." (PMID 38132438, 2023). "In human glioma cells, SOX21 overexpression inhibits SOX2 expression and induces apoptosis because of the interaction between SOX21 and SOX2." (PMID 27933111, 2016). "Westermark and his colleagues reported that another Sox family protein, Sox21, is expressed in glioma cells." (PMID 22111550, 2012). "Sox21 is an antagonizing partner of Sox2 and negatively regulates the expression of Sox2 in glioma cells." (PMID 22111550, 2012). "On the other hand, we found that sustained as well as transient induction of Sox21 can inhibit Sox2 expression, a result similar to that previously obtained in human glioma cell lines." (PMID 23071561, 2012). "In glioma, the increased SOX21 expression inhibits SOX2 leading to cancer cell apoptosis." (PMID 38132438, 2023). "In glioma, SOX21 is a tumor suppressor with a repression activity during tumorigenesis." (PMID 38132438, 2023). "SOX21 was recently proposed to act as a tumour suppressor in glioma, after observations that the SOX2:SOX21 balance determines cellular choice between a stem-like state and differentiation." (PMID 29089486, 2017). "Moreover, the overexpression of SOX21 forms a complex with SOX2, altering the balance and composition of SOX2 and SOX21, consequently inducing apoptosis in glioma cells." (PMID 38331879, 2024). "Although MED10 (P = 0.5332) and SOX21 (P = 0.2831) exhibited no differential expression in glioblastoma and normal tissues, they may exhibit differential expression between glioblastoma and low-grade glioma." (PMID 30382873, 2018).
colorectal cancer (4 papers, 2014 to 2021). A primary or metastatic malignant neoplasm that affects the colon or rectum. "For example, SOX21 has been reported to be closely related to the tumorigenesis of glioblastoma, hepatocellular carcinoma, and colorectal cancer." (PMID 32211318, 2020). "A previous study revealed that SOX21 expression was controlled through DNA methylation and was a suitable biomarker for colorectal cancer diagnosis." (PMID 27933111, 2016). "For other genes, e.g. FOXI2 and SOX21, their methylation in colorectal cancer has not previously been reported, but they are likewise supported by Infinium Human Methylation 27 K microarray data from the TCGA consortium." (PMID 24485021, 2014).
glioblastoma (3 papers, 2018 to 2026). The most malignant astrocytic tumor (WHO grade IV). "Among the genes in this model, OSMR and SOX21 have been previously reported in glioblastoma studies." (PMID 30382873, 2018).
alopecia (2 papers, 2017 to 2020). Hair loss usually from the scalp. "Sox21 also regulates differentiation of hair cuticle, and Sox21 null mice develop cyclic alopecia." (PMID 33255698, 2020). "However, the level of Sox21 remained unaltered in Msx2 null background suggesting independent mode of action of both the molecules in the development of cyclic alopecia." (PMID 28912581, 2017).
brain inflammation (2 papers, 2023 to 2024). "The interaction of miR-181b-2-3p and its target SRY-related high-mobility group box transcription factor 21 (Sox21) plays a duel role in brain inflammation and the impairment of neurogenesis induced by ionizing radiation through inducing apoptosis in neurogenic zones and activating microglia." (PMID 39451223, 2024). "The present study employed multiple methods—immunohistochemistry, real-time RT-PCR, western blot, ELISA, cell proliferation and cytotoxicity assay—to examine the roles of miR-181b-2-3p and SOX21 in radiation-induced brain inflammation and the impairment of neurogenesis both in vivo and in vitro." (PMID 36831315, 2023).
breast carcinoma (2 papers, 2016 to 2017). "Homozygous deletions over or near SOX21 were found in three cases of multiple myeloma, one lymphoma and one breast cancer." (PMID 29089486, 2017).
cervical cancer (2 papers, 2022 to 2025). A primary or metastatic malignant neoplasm involving the cervix. "SOX21 promotes the progression of colon cancer, pancreatic cancer, cervical cancer and nephroblastoma." (PMID 39889187, 2025).
colon cancer (2 papers, 2015 to 2025). "Interestingly, it was previously demonstrated that Sox21 is induced by Sox2, and, unlike Sox2, Sox21 negatively regulates transcription of Cdx2 in mES and colon cancer cells." (PMID 26783396, 2015).
pancreatic cancer (2 papers, 2025). "On the contrary, in pancreatic cancer, up-regulation of SOX21 by STAT6-activated SOX21-AS promotes cancer cells malignancy." (PMID 40141294, 2025).
small cell lung carcinoma (2 papers, 2007 to 2018). Small cell lung cancer (SCLC) is a highly aggressive malignant neoplasm, accounting for 10-15% of lung cancer cases, characterized byrapid growth, and early metastasis. "Thus, SOX1, SOX2, SOX3 and SOX21 as well as SOX4 were demonstrated to elicit humoral immune responses in small cell lung cancer patients." (PMID 17375044, 2007). "Despite these evidence, studies in small cell lung cancers suggest that SOX21 promotes proliferation rather than differentiation and expression of SOX21 in mouse embryonic stem cells (ESCs) induced the expression of SOX2 and thus maintained their pluripotency." (PMID 29867344, 2018).
acne (1 paper, 2024). An inflammatory process of the sebaceous glands which is characterized by comedones, nodules, papules and/or pustules on the skin. "SOX21 burden was associated with increased acne (OR=1.01, p=6.9× 10−7 ) and spinocerebellar disease (OR=1.01, p=2.3× 10−6)." (PMID 39132489, 2024).
lung diseases (1 paper, 2023). "Given that hyperplasia of NE cells and defective clustering are associated with several lung diseases and NE function respectively, investigating the molecular mechanisms downstream of SOX2 and SOX21 may provide new insight in NE function and development of new therapeutic approaches." (PMID 36867267, 2023).
osteoporosis (1 paper, 2020). A condition of reduced bone mass, with decreased cortical thickness and a decrease in the number and size of the trabeculae of cancellous bone (but normal chemical composition), resulting in increased fracture incidence. "We found that disruption of Sox21 caused severe enamel hypoplasia, regional osteoporosis, and ectopic hair formation in the gingiva in Sox21 knockout incisors." (PMID 32674056, 2020).
tumor (14 papers, 2007 to 2026). "Induced SOX21 expression in GPCs within pre-established GBM reduces their capacity to sustain tumor growth and significantly extends the survival of the orthotopically transplanted mice." (PMID 41620461, 2026). "Mechanistically, SOX21 functions as a tumor suppressor by binding a large set of AP-1-targeted chromatin regions, leading to epigenetic repression of AP-1-activated genes." (PMID 41620461, 2026). "SOX21 plays a tumor suppressor role in central nervous system tumors as a complexing SOX1–3 inhibitor." (PMID 40141294, 2025). "Here in this case, Sox21 mutant EBs can be regarded as the tumor-initiating cells in vivo." (PMID 27187149, 2016). "Our findings identify SOX21 as a key regulator that prevents GPC malignancy by targeting and repressing an AP-1-driven, tumor-promoting gene expression program." (PMID 41620461, 2026). "We observed statistically significant differences in the expression of SOX6, SOX8, SOX21 and SOX30 genes in healthy tissue vs. primary tumor samples." (PMID 38132438, 2023). "We demonstrated statistically significant differences in expression between normal and primary tumor tissues for SOX6, SOX8, SOX21 and SOX30 genes and pointed to SOX6 as the one that met the independent diagnostic markers criteria." (PMID 38132438, 2023). "SOX21, the counteracting partner of SOX2, functions as a tumour suppressor during gliomagenesis by negatively regulating SOX2." (PMID 30382873, 2018).
cancer (10 papers, 2014 to 2024). A tumor composed of atypical neoplastic, often pleomorphic cells that invade other tissues. "Whereas the association with HERVH-CALB1 expression extended to other cancer types for some transcription factors (SOX2, SOX21), for others (TP63, FOXE1), it was specific to LUSC." (PMID 37192000, 2023). "Of the genes tested in plasma, BCAT1, GRASP, IKZF1, IRF4, SDC2, SEPT9 and SOX21 exhibited high sensitivity (≈55% or greater) for detection of methylated ctDNA in cancer patients." (PMID 27983717, 2016).
SOX21 also shares sentences with these, for which no sentence is quoted: adenoma (2 papers); lung carcinoma (2); bipolar disorder (1); chordoma (1); colorectal tumors (1); esophageal squamous cell carcinoma (1); hepatocellular carcinoma (1); infection (1); lung squamous cell carcinoma (1); lymphoma (1); multiple myeloma (1); Nephroblastoma (1); schizophrenia (1).